BRD9 (bromodomain containing 9)
Diseases named in the same sentence as BRD9 in open-access papers (continued):
Sharing a sentence is not in itself a finding about the gene and the disease.
leukemia (18 papers, 2016 to 2025). A malignant (clonal) hematologic disorder, involving hematopoietic stem cells and characterized by the presence of primitive or atypical myeloid or lymphoid cells in the bone marrow and the blood. "Among them, BRD9 was recently linked to oncogenic roles in the tumorigenesis processes, especially in sarcomas and leukemias." (PMID 40343767, 2025). "Furthermore, Brd9 loss induces a preleukemia-like phenotype of differentiation block and retention of a leukemia-associated transcriptional program, related, at least in part, to the failure to transition from ‘progenitor transcription factor programs’ to later differentiation programs." (PMID 37580596, 2023). "BI-7271, BI-7273, and BI-9564 are potent selective BRD9 inhibitors that suppress leukemia cell proliferation." (PMID 38390898, 2024). "We therefore investigated the ability of BRD9 targeting to potentiate agents that are the standard of care in leukemia, such as decitabine, ATRA, and 5-azacytidine, as well as more targeted agents, such as venetoclax and olaparib." (PMID 35853853, 2022). "BRD9 has previously been reported to maintain leukemia cells in a proliferating and undifferentiated state." (PMID 35853853, 2022). "To further characterize the role of Brd9&Jmjd6 and Kat6a&Jmjd6 in leukemia, we performed RNA-seq to compare the global transcriptional changes upon either single or double genetic perturbation of the targeted genes." (PMID 32661245, 2020). "This screen reveals synthetic sick interactions between Brd9&Jmjd6, Kat6a&Jmjd6, and Brpf1&Jmjd6 in leukemia cells." (PMID 32661245, 2020). "Collectively, our findings identify BRD9 as a driver sustaining proliferation and survival of leukemic cells, and point to its potential as a therapeutic target in leukemia." (PMID 31000698, 2019). "As for the downstream pathways of BRD9, a recently study for leukemia reported that BRD9 promote the survival of AML cells mainly via STAT5 activation." (PMID 31504061, 2019). "Our data provide new insights into the function of BRD9 in cancer and suggest BRD9 as a novel potential therapeutic target in leukemia." (PMID 31000698, 2019). "Taken together, these results show that BRD9 is a key regulator for STAT5 activation in leukemia via regulation of SOCS3 expression." (PMID 31000698, 2019). "Our findings identify a previously undescribed BRD9-STAT5 axis as critical for leukemia maintenance, suggesting BRD9 as a potential therapeutic target." (PMID 31000698, 2019). "Accordingly, inhibition of BRD9 in leukemia reduces STAT5 activation and induces apoptosis via Caspase8 and not Caspase9 cleavage." (PMID 31000698, 2019). "To investigate the potential involvement of BRD9 in leukemia, we assayed the biological effects of shRNA-mediated BRD9 knockdown (KD) on leukemic cell growth." (PMID 31000698, 2019). "Taken together, these data indicate that BRD9 is overexpressed in both leukemia and solid cancer cells." (PMID 31000698, 2019). "To explore BRD9 upregulation in leukemia, we analyzed epigenetic marks in BRD9 regulatory regions of AML patient’s cohort compared with normal progenitors and differentiated cells; unfortunately, we did not highlight significative differences between them." (PMID 31000698, 2019). "Relevant to this, a BRD9 bromodomain-specific inhibitor was earlier developed and shown to have efficacy in inhibiting leukemia cell proliferation." (PMID 31015438, 2019). "BRD9 is important for sustaining MYC expression via its BRD in diverse MLL-r leukemia cell lines, including MV4-11, MOLM-13, ML-2, EoL-1, and NOMO-1." (PMID 31157223, 2019). "Additionally, there is evidence suggesting that BRD9 plays a role in activating oncogenes in leukemias and lung cancer." (PMID 39971779, 2025). "The protein Bromodomain-containing protein 9 (BRD9), a crucial part of the ncBAF variant of the SWI–SNF chromatin remodeling complex, has been identified as a potential therapeutic target in a subset of sarcomas and leukemias." (PMID 38675453, 2024).
leukemia (continued). "We therefore next investigated the effects of Brd9 depletion on leukemia maintenance." (PMID 38102116, 2023). "dBRD9-A is a previously-described BRD9 degrader with activity in leukemia." (PMID 35853853, 2022). "Consequently, inhibiting BRD9 may represent not only a possible approach to targeting leukemia but also an alternative strategy to target pSTAT5-driven tumors." (PMID 31000698, 2019). "Thus, BRD9 upregulation in leukemia could be due to a genetic alteration or overexpression of “positive BRD9 regulators”." (PMID 31000698, 2019). "BRD9, a component of the BAF SWI/SNF complex, has been reported to be over-expressed in MPM and leukemia." (PMID 32927435, 2020). "Bromodomain-containing protein 9 (BRD9), an essential component of the SWI/SNF chromatin remodeling complex termed ncBAF, has been established as a therapeutic target in a subset of sarcomas and leukemias." (PMID 35853853, 2022). "By using western blotting analysis, the BRD9 protein levels in CD34+ cell and some cancer cell lines (HL60, K562 and U937) were compared, another research represented that this protein was also elevated in leukemia and lymphoma." (PMID 31504061, 2019). "Among them, the effect of I-BET151 on BRD9 may be indirect because BRD9 and BRD4 form a complex.I-BET151 selectively inhibits leukemia mouse models and mixed-lineage leukemia (MLL) primary patient samples, and its half-life is significantly longer than that of similar BET inhibitors (JQ1, I-BET762)." (PMID 34540687, 2021). "Knockdown of BRD9 impaired cell growth in RN2 cells and in a panel of human leukemia cell lines, but not in human epithelial cell lines or in mouse embryonic fibroblasts." (PMID 36810086, 2023).
melanoma (14 papers, 2020 to 2024). A malignant, usually aggressive tumor composed of atypical, neoplastic melanocytes. "Surprisingly, there was an additive effect on HEK293T cell growth upon addition of both AraC and I-BRD9; we suspect this to be due to a role for BRD9 in DNA repair, which has been identified through rare melanoma variant screening." (PMID 38126767, 2024). "Loss of BRD9 promoted melanoma proliferation in vitro and tumor growth and metastasis in vivo and correction of the poison exon in BRD9 using antisense oligonucleotides slowed tumor growth." (PMID 35323214, 2022). "Altogether, these results suggested that CDH23, ARHGEF40, and BRD9 genes could be also important for sporadic melanoma and consequently, a mutation in these genes could be pivotal in this disease." (PMID 32276436, 2020). "Since CDH23, ARHGEF40, and BRD9 function is unclear, the impact of rare variants in these genes in melanoma context is unknown." (PMID 32276436, 2020). "ARHGEF40 and BRD9 were mutated in 18 of 448 melanoma patients (4%)." (PMID 32276436, 2020). "A study has shown that TP‐472 as a BRD9/7 inhibitor can inhibit melanoma tumour growth by promoting apoptosis." (PMID 38303608, 2024). "A positive correlation was observed between BRD9 expression and the estimated number of MDSCs for most cancer types including melanoma." (PMID 38303608, 2024). "Based on spatial transcriptome data, BRD9 was shown to be highly expressed in tissues of melanoma patients." (PMID 38303608, 2024). "We further explored the potential of combination therapy of anti‐BRD9 and anti‐PD‐1 in melanoma, utilising data from GSE91061." (PMID 38303608, 2024). "BRD9 has the potential to serve as a therapeutic target, when pairing with etoposide in patients with melanoma." (PMID 38303608, 2024). "TP-472, a compound with selective function and similarity to the bromodomain of BRD7 and BRD9, has antitumor activity on melanoma." (PMID 36844227, 2023). "TP-472, a drug that is selective for the highly similar bromodomains of BRD7 and BRD9, markedly inhibited melanoma growth and invasion." (PMID 35323214, 2022). "Examinations of Human Protein Atlas datasets revealed that overexpression of BET family BRD proteins (i.e., BRD2 and BRD3), BRD9, BRD7, and EZH2 were associated with relatively poor three-year survival in melanoma patients." (PMID 34771678, 2021). "Overall, the data available in the literature regarding BRD9 function coupled with our data from Gene Ontology analysis further highlights the importance of studying this gene in the context of melanoma." (PMID 32276436, 2020). "We first validated the on-target gene editing effects of Brd9&Jmjd6 and Kat6a&Jmjd6 dual-crRNAs in RN2c12 and B16-F10c12 melanoma cells." (PMID 32661245, 2020). "BRD9 could potentially serve as a novel biomarker for diagnosing different cancer types, especially could accurately forecast the prognosis of melanoma patients receiving anti‐programmed cell death 1 immunotherapy." (PMID 38303608, 2024). "It was recently reported that BRD9 is over-expressed in melanoma and that high expression of BRD9 correlates with poorer survival and that it may be a therapeutic target." (PMID 35323214, 2022). "Finally, the inhibition of BRD9 poison exon inclusion by using specific antisense oligonucleotides (ASOs) rescues BRD9 expression in SF3B1MUT melanoma cells in vitro and inhibits tumor growth by inducing tumor necrosis in vivo." (PMID 35053445, 2022).
melanoma (continued). "Interestingly, in the 57,490,258–58,411,259 pb region of chromosome 21 associated with two traits (VM and VN), we found five candidate genes (LPCAT1, CLPTM1L, TERT, TRIP13, and BRD9), all of which were related to the main types of skin cancer, i.e., melanoma and cutaneous squamous cell carcinoma." (PMID 39199954, 2024). "Finally, it was recently reported that the bromodomain-containing 9 (BRD9) gene is over-expressed in melanoma and that a high expression of BRD9 correlates with poorer survival, suggesting that it may be a therapeutic target." (PMID 39199954, 2024). "Thus, there is evidence that in some melanomas with SF3B1 mutations and loss of BRD9, an approach which restores BRD9 expression may potentially be therapeutically useful." (PMID 35323214, 2022). "TP-472, which has less selectivity for BRD9 over BRD7 compared to other BRD9 inhibitors, blocked melanoma tumorigenicity and tumor growth in vivo as well as suppressed the proliferation of uterine leiomyosarcoma cells." (PMID 38390898, 2024). "These include some canonical melanoma tumor-suppressive genes such as BRD9 and CDKN2A/CDKN2B, and several critical melanoma oncogenes like BIRC5 and YAP1." (PMID 37904237, 2023). "The results of immunohistochemistry analyses of melanoma tissues from the Human Protein Atlas indicated that BRD7, BRD9, BRD4, BRD3, and KDM6B were mostly expressed at >75% level." (PMID 34771678, 2021). "Validating experiments showed that BRD9 KD in non-tumorigenic Melan-a melanocytes results in tumor growth and the induction of melanomagenesis in vivo while BRD9 depletion in melanoma cells increases the number of pulmonary metastases." (PMID 35053445, 2022).
rhabdoid tumor (11 papers, 2017 to 2025). An aggressive malignant embryonal neoplasm usually occurring during childhood. "Small-molecule BRD9 inhibitors have been shown to reduce the proliferation of SMARCB1-deficient rhabdoid tumor cells in vitro and induce G1 cell cycle arrest." (PMID 40115023, 2025). "BRD9 inhibition in rhabdoid tumors resulted in decreased cell proliferation, G1-arrest, and apoptosis." (PMID 32908135, 2020). "Here, using a genome-wide CRISPR-Cas9 screen, we show that BRD9 is a specific vulnerability in pediatric malignant rhabdoid tumors (RTs), which are driven by inactivation of the SMARCB1 subunit of SWI/SNF." (PMID 31015438, 2019). "Interestingly, both NEUROG1 and NEUROD2 were hypermethylated and down-regulated in AT/RTs when compared to MBs in our DM-DE gene analysis and they harbor DMRs, which were hypermethylated in AT/RTs compared with PSCs and bound by BRD9 in rhabdoid tumors." (PMID 38499326, 2024). "In SMARCB1-null rhabdoid tumors, the presence of BRG1 and the non-canonical SWI/SNF subunit, BRD9, are synthetic lethal targets in rhabdoid cancers, although the mechanisms by which they maintain a rogue gene expression program are not entirely clear." (PMID 38473277, 2024).
ovarian carcinoma (9 papers, 2019 to 2024). A malignant neoplasm originating from the surface ovarian epithelium. "Analysis of the TCGA database showed that BRD9 is amplified in 15% of ovarian cancer patients, and higher expression of BRD9 is associated with poor outcome in ovarian cancer patients undergoing platinum-based treatment." (PMID 32457312, 2020). "Previous studies have found that BRD9 is upregulated in ovarian cancer, and depleting BRD9 makes cancer cells more sensitive to olaparib and cisplatin." (PMID 34149798, 2021). "In this study, we further discovered that inhibition of BRD9 using I-BRD9 sensitizes ovarian cancer cells to cisplatin and PARP inhibitor in vitro and in xenograft mice models." (PMID 32457312, 2020). "Next, we assessed the expression of BRD9 in a number of ovarian cancer and normal cell lines, and found that BRD9 was overexpressed in multiple ovarian cancer cell lines." (PMID 32457312, 2020). "In order to evaluate the potential role of BRD9 in therapeutic response, we assessed publicly available data from the TCGA database, and found that BRD9 is amplified in about 15% of ovarian cancers." (PMID 32457312, 2020). "BRD9 is overexpressed in ovarian cancer and depleting BRD9 sensitizes cancer cells to olaparib and cisplatin." (PMID 32457312, 2020). "Because BRD9 is overexpressed in ovarian cancer, and targeting BRD9 sensitizes ovarian cancer to PARP inhibition and cisplatin, we show that BRD9 is a promising target to overcome therapeutic resistance in this disease." (PMID 32457312, 2020). "In order to investigate BRD9 as a potential target for ovarian cancer therapy in vivo, we assessed the sensitivity of control and BRD9 KD OVCAR8 cells to olaparib in xenograft models." (PMID 32457312, 2020). "BRD9 was amplified in bladder cancer (10.17%), lung squamous cell carcinoma (19.37%), lung adenocarcinoma (15.02%), esophageal carcinoma (14.52%) and ovarian cancer (13.53%)." (PMID 31504061, 2019). "To further test the function of BRD9 in cancer, we knocked down BRD9 expression in four breast and ovarian cancer cell lines with short hairpin RNAs (shRNAs), then analyzed cell growth in both anchorage-dependent and -independent conditions." (PMID 30760718, 2019). "Another study found BRD9 depletion increased cancer cell chemotherapy sensitivity as well as sensitivity to olaparib in Ovarian cancer, suggesting a drug targeting BRD9 may work synergistically with olaparib." (PMID 34944438, 2021). "Another bromodomain‐containing protein of significance to ovarian cancer is BRD9." (PMID 34213777, 2021). "Targeting BRD9 may be synergistic with adjuvant radiotherapy, with one study finding BRD9 sensitised ovarian cancer cell lines to radiotherapy." (PMID 34944438, 2021). "Collectively, these results support our hypothesis that BRD9 amplification in ovarian cancers may confer higher HR activity and resistance to chemotherapy." (PMID 32457312, 2020). "Considering that BRD9 is amplified in a subset of ovarian cancers, a combination of BRD9 inhibitor I-BRD9 and platinum or PARP inhibitors may provide a therapeutic approach to HR-proficient cancers." (PMID 32457312, 2020). "Immunofluorescence assay identified that BRD9 was highly expressed in most cancer cell lines, such as epidermoid carcinoma cell line A‐431, human osteosarcoma cell line U‐2 OS, human glioblastoma cell line U‐251 MG, human ovarian carcinoma cell line EFO‐21 and squamous cell carcinoma cell line SiHa." (PMID 38303608, 2024). "By analyzing the TCGA database and performing HR repair screening, we demonstrated that three BRD-containing proteins, BRD9, ASH1L, and ZMYND8, positively regulate HR, and the mutations of these three BRD-containing proteins are associated with HR-deficient mutational signatures in ovarian cancer." (PMID 32457312, 2020). "Furthermore, the combination of PARPi/platinum and BRD9 inhibitor may help overcome chemoresistance in ovarian cancer, especially those overexpressing BRD9." (PMID 32457312, 2020).
ovarian carcinoma (continued). "To further examine the potential role of BRD9 as a target for cancer therapy, we knocked down BRD9 in OVCAR8 and OVCAR10 cells, ovarian cancer cell lines with high expression of BRD9, and performed colony-formation assays following olaparib, cisplatin, etoposide, and IR treatment." (PMID 32457312, 2020). "A recent study demonstrated that BRD9 levels are in fact elevated in ovarian cancer, and that inhibition sensitizes ovarian cancer to PARP inhibition and cisplatin therapy through regulation of the DNA damage response machinery—a frequently disrupted pathway in ovarian cancer." (PMID 34213777, 2021).
prostate carcinoma (9 papers, 2021 to 2025). A carcinoma that arises from epithelial cells of the prostate gland. "This work aims to characterise BRD9, currently understudied in prostate cancer, and investigate its co-expression with other genes to assess its potential as a biomarker and therapeutic target in human prostate cancer." (PMID 34944438, 2021). "BRD9 is co-expressed with many genes in the SWI/SNF and BET complexes, as well as those in common signalling pathways in prostate cancer." (PMID 34944438, 2021). "BRD9 also shows promise as a therapeutic target, particularly in advanced prostate cancer, and as a co-target alongside other genes in the SWI/SNF and BET complexes, and those in common prostate cancer signalling pathways." (PMID 34944438, 2021).
sarcoma (8 papers, 2018 to 2025). A usually aggressive malignant neoplasm of the soft tissue or bone. "We indicated that elevated BRD9 expression was linked to an adverse prognosis, with regards to OS, for adrenocortical carcinoma (ACC), LIHC, mesothelioma (MESO) and sarcoma (SARC) cohorts." (PMID 38303608, 2024). "Moreover, consistent with our genetic data other pediatric sarcoma subtypes are unaffected by BRD9 degradation." (PMID 30431433, 2018). "For BRD9, we discovered that the survival time of patients with 3 cancer types was significantly shorted by high mRNA expression of BRD9: liver cancer (HR, 1.72; 95% CI, 1.21 to 2.46), ccRCC (HR, 1.54; 95% CI, 1.11 to 2.12), and sarcoma (HR, 1.78; 95% CI, 1.17 to 2.71)." (PMID 31504061, 2019).
squamous cell lung carcinoma (8 papers, 2019 to 2024). A carcinoma arising from squamous bronchial epithelial cells. "Over-expression of miR-140-3p negatively affected the tumorigenesis by down-regulating the oncogene BRD9 in squamous cell lung cancer." (PMID 32927435, 2020). "Previous reports showed that miR‐140‐3p is downregulated in squamous cell lung cancer and functions as a tumor suppressor by targeting bromodomain containing 9 in vitro and in vivo." (PMID 31199049, 2019). "Other authors have reported that miR-140-3p could suppress tumorigenesis of squamous cell lung cancer by regulating the expression of BRD9." (PMID 35654787, 2022). "has-miR-140-3p downregulates the oncogene BRD9 (bromodomain containing 9) expression in squamous cell lung cancer (SqCLC) and inhibits SqCLC tumorigenesis, thus may become a new inhibitor of SqCLC." (PMID 35310909, 2022).